IL6 (interleukin 6)
Diseases named in the same sentence as IL6 in open-access papers (continued):
Sharing a sentence is not in itself a finding about the gene and the disease.
Parkinson disease (continued). "However, accumulating evidence shows that Parkinson’s disease is accompanied by immune responses that lead to an increase in serum levels of pro-inflammatory cytokines such as interleukin-6 (IL6), tumor necrosis factor alpha (TNFα), interleukin-1β (IL1B), and interferon gamma (IFNG)." (PMID 32274386, 2020). "Interestingly, miR-190 was involved in neuroinflammation as its upregulation inhibited the expression of inducible nitric oxide synthase and other proinflammatory cytokines as IL-6, while it increased the expression of anti-inflammatory cytokines such as IL-10 in a Parkinson’s disease mouse model." (PMID 32531989, 2020). "In Parkinson’s disease patients, SATB1 (a CDKN1A inhibitor) levels are reduced in the substantia nigra, while CDKN2A, MMP3, IL-6, IL-1α, and CXCL8 levels are elevated, indicating an increased aging burden." (PMID 39963130, 2025). "In a Parkinson’s model, FTY720-NPs injections reducedMPO and NOS activity, downregulated IL-6 and TNFα, and shiftedmicroglia from M1 to M2 phenotype." (PMID 39965088, 2025). "H. pylori infection induces the secretion of pro-inflammatory cytokines, such as TNF-α and IL-6, which can cross a compromised BBB and contribute to dopaminergic neuronal death, promoting parkinsonism." (PMID 39202269, 2024). "The lesion of substantia nigra in Parkinson’s disease is upregulated and produced higher levels of inflammatory factors, TNF-α, Interleukin-6, and interferon gamma." (PMID 38600296, 2024). "Our findings report that MP can attenuate motor and olfactory dysfunction in rotenone-intoxicated PD mouse model and downregulate IL-6, IL-12p40, and TGF-β1 in mice serum, suggesting its effective role in anti-parkinsonism." (PMID 39194762, 2024). "Linalool decreased the IL-6 secretions of the SH-SY5Y cells in all three experimental models, even if rotenone or 6-OHDA were used as Parkinson’s inducer." (PMID 39199163, 2024). "I is reported that oral treatment with escin diminished behavioural impairments, oxidative stress and inflammation in the chronic MPTP/probenecid mouse model of Parkinson’s disease (PD) by reducing the levels of TNF-α, IL-6, IL-4, IL-10, SOD and catalase." (PMID 36830684, 2023). "In a study of Parkinson's disease, ANKRD22 obtained through bioinformatics screening was shown to regulate neuronal development by regulating cell viability and IL-6 expression." (PMID 38102696, 2023). "In a mouse model of Parkinson’s disease, metformin (150 mg/kg) reduced the amount of microglia, proinflammatory cytokines (TNF-α, IL-1β, and IL-6), and inducible nitric oxide synthase (iNOS)." (PMID 37759689, 2023). "CONPs suppressed the neuronal inflammatory responses by lowering the high levels of IL-6 and TNF-α and hence demonstrating the effectiveness of the produced CONPs in Parkinson’s disease." (PMID 37324485, 2023). "Inflammation in the brain contributes to the development of Alzheimer’s and Parkinson’s diseases, and pathological studies have shown that increased levels of COX-2, PGE2, IL-6, and TNF-α play a role in these degenerative brain diseases." (PMID 35054942, 2022). "In a mouse model of Parkinson’s disease, EGCG treatment can effectively reduce the expression of serum inflammatory factors including TNF-α and IL-6." (PMID 35409364, 2022). "CUR also decreased pro-inflammatory cytokines (IL-6, IL-1, and TNFα) in the 1-methyl-4-phenyl-1,2,3,6-tetrahydropyridine (MPTP) model of Parkinson’s disease (PD) and protected dopaminergic neurons from degeneration." (PMID 35216083, 2022). "The Nrf2 pathway regulates the expression of inflammatory biomarkers inducible NO synthase, interleukin 6 (IL-6), tumor necrosis factor-alpha (TNF-α), as well as the microglial function and neuroinflammation as in cases of Parkinson’s disease." (PMID 35694174, 2022). "There are a set of pro-inflammatory cytokines including IL-6, TNF, IL-1β, and IFN-γ in the serum of patients with Parkinson's disease." (PMID 32983119, 2020).
Parkinson disease (continued). "Further, specific inflammatory responses were observed with microglial activation and increased expression of pro-inflammatory cytokines (like IL-6, TNF-α), specifying role for TiO2 NPs in neuroinflammation - a key driver in diseases like Alzheimer’s and Parkinson’s." (PMID 41409624, 2025). "Second, although previous studies have reported elevated levels of pro-inflammatory cytokines such as TNF-α, IL-1β, and IL-6 in the CSF of MSA patients compared to those with Parkinson’s disease, we did not detect similar cytokine increases in our mouse model." (PMID 40336104, 2025). "Studies have shown that patients with Parkinson’s disease with H. pylori infection exhibit higher levels of pro-inflammatory cytokines, such as TNF-α and IL-6, which may contribute to disease progression." (PMID 39202269, 2024). "Also, in a mouse model of Parkinson's disease, MET reduced the numbers of microglia and proinflammatory cytokines TNF‐α, IL‐1β, IL‐6, and iNOS." (PMID 33443781, 2021). "Furthermore, PYC shows neuroprotective effects through antioxidant and anti-inflammatory potency, in traumatic brain injury and Parkinsonism mouse models and inhibited the upregulation of TNF-α, IL-6 and IL-1β." (PMID 26367267, 2015). "The research hypothesizes that CTE can modulate key biomarkers involved in Parkinson’s pathology, including α-synuclein, interleukin-1β (IL-1β), and tumor necrosis factor-α (TNF-α), assessed through qRT-PCR, as well as interleukin-6 (IL-6) and TNF-α, evaluated through ELISA." (PMID 39642134, 2024). "The mRNA expression and protein expression of inflammatory factors (TNF-α, IL-6 and IL-1β) in the substantia nigra were respectively measured by RT-qPCR and ELISA to assess the effect of elevated miR-375 in inflammatory response of 6-OHDA-induced Parkinson’s disease rats." (PMID 31927536, 2020). "No cytokine was a specific marker for parkinsonism, but TNF-α, CPP, IL-1β, IL-4, and IL-6 may be useful for early differentiation of atypical parkinsonism to PD." (PMID 30390673, 2018).
acute pancreatitis (175 papers, 2005 to 2026). An acute inflammatory process that leads to necrosis of the pancreatic parenchyma. "This systematic review demonstrates that both IL-6 and Ang-2 have meaningful diagnostic and prognostic value in the early risk stratification of adults with acute pancreatitis." (PMID 41590239, 2026). "Across all included studies, IL-6 was associated with severe acute pancreatitis, although its diagnostic accuracy varied considerably." (PMID 41590239, 2026). "The aim of this study is to assess the prognostic significance of thromboelastogram parameters, interleukin-6, and interleukin-22 levels in assessing the risk for developing severe forms of acute pancreatitis." (PMID 39694959, 2024). "Both TNFα and IL-6 are implicated in the regulation of apoptotic and necrotic pathways, influencing the balance between cell survival and death in the pancreas during acute pancreatitis." (PMID 38927047, 2024). "Inflammatory factors, such as IL-2, IL-6, and IL-10, are closely associated with acute pancreatitis." (PMID 38424643, 2024). "PGC-1α deficiency can up-regulate IL-6 expression by enhancing the NF-kB signaling during the process of acute pancreatitis." (PMID 37679346, 2023). "This study aimed to evaluate changes in IL-6 concentration and the concentration/activity of superoxide dismutase isoenzymes (SOD1, SOD2, and SOD3) in the blood of patients with acute pancreatitis (AP) in terms of rs1800795 polymorphism in the IL6 gene." (PMID 35205334, 2022). "Among inflammatory mediators, serum level of interleukin-6 (IL-6) reflects the severity of acute pancreatitis and acute lung injury associated with severe acute pancreatitis." (PMID 34349610, 2021). "The findings of this systematic review demonstrate that Ang-2 and IL-6 represent two fundamental and complementary components of the early pathophysiology of acute pancreatitis, offering valuable opportunities for risk stratification within the first hours and days of disease onset." (PMID 41590239, 2026). "In addition, the IL-6 serum concentration was significantly increased in patients with severe acute pancreatitis with associated gut microbiota alterations compared to patients with severe pancreatitis without changes in the gut microbiota." (PMID 38540258, 2024). "We confirmed that CRP and elastase analyzed on the third day of admission, in addition to the evaluation of IL-6, IL-8, IL-10, and sTNFr on the first day, represent a valuable diagnostic tool in the assessment of severity and course of disease in patients with acute pancreatitis." (PMID 23476635, 2013). "Overall, this systematic review confirms that IL-6 and Ang-2 are highly informative early biomarkers of severe acute pancreatitis." (PMID 41590239, 2026). "Comparison of IL-6 and Ang-2 shows that the two biomarkers reflect distinct yet closely interconnected components of the early pathophysiology of acute pancreatitis." (PMID 41590239, 2026). "First, heterogeneity of the available data remains a limitation for the development of uniform clinical recommendations for IL-6 and angiopoietin-2 in acute pancreatitis." (PMID 41590239, 2026). "Further experiments are need to address the IL-6 mediated T cell differentiation and to decipher the role of T cell subclasses during acute pancreatitis." (PMID 40560328, 2025). "In serum samples of patients suffering from acute pancreatitis we observed a severity-dependent increase of IL-6 and OSM." (PMID 40560328, 2025). "After the onset of acute pancreatitis IL-6 serum levels increase rapidly and affect the systemic immune reaction." (PMID 40560328, 2025). "The depletion of T cells or a diminished activation by IL-6 attenuate the disease severity in a mild model of acute pancreatitis and suggest a critical role of T cells in the immune regulation during acute pancreatitis." (PMID 40560328, 2025). "The study highlights that both IL-6 and IL-22 play crucial roles in the inflammatory cascade of severe acute pancreatitis." (PMID 39694959, 2024).
acute pancreatitis (continued). "The goal of this study is to evaluate the prognostic significance of inflammatory markers (interleukin-6 and interleukin-22), their dynamics and hemostatic parameters in predicting the development of severe acute pancreatitis (SAP)." (PMID 39694959, 2024). "Serum levels of interleukin (IL)‐1β, IL‐5, IL‐6, IL‐8, IL‐10, IL‐17, and tumor necrosis factor‐α were significantly higher in the severe acute pancreatitis (SAP) group than in the non‐SAP group (p < .05)." (PMID 38411379, 2024). "IL-6 demonstrates significantly elevated serum levels in cases of necrotizing pancreatitis and severe acute pancreatitis on the day of admission, making it an excellent marker for early severity stratification and predicting remote organ failure." (PMID 38279274, 2024). "IL-6 levels were significantly elevated in patients with severe acute pancreatitis compared to those with milder forms." (PMID 39694959, 2024). "The severity of pancreatic pathological injuries in acute pancreatitis correlates significantly with the levels of infiltrated inflammatory cell-mediated cytokines, such as IL-1β, IL-6, and tumor necrosis factor-alpha (TNF-α)." (PMID 38550755, 2024). "Ali and Madkour suggested that the tissue concentrations of TNF-α, IL-6, and IL-1β in the melatonin pretreatment group were significantly lower than in the L-arginine-induced acute pancreatitis group." (PMID 38333760, 2024). "One of the hallmarks f acute pancreatitis is the increased levels of the proinflammatory cytokine IL-6, which is released by macrophages that become activated within the inflamed pancreas." (PMID 38910880, 2024). "IL-6 was found to have the best sensitivity and specificity for the early assessment of severe acute pancreatitis." (PMID 39337656, 2024). "In a rat model of liver injury associated with severe acute pancreatitis, the inhibitor AG490 of JAK2 effectively reduced the serum levels of TNF, IL-6, and IL-18 by blocking excessive JAK2 and STAT3 activation." (PMID 38543164, 2024). "Based on the results, the study underscores the significant role of interleukins, particularly IL-6 and IL-22, as well as specific hemostasis parameters, in the development and prognosis of severe acute pancreatitis (SAP)." (PMID 39694959, 2024). "It has been suggested that proinflammatory cytokines such as IL-1β, TNF-α, and IL-6 are local and systemic mediators and play a role in the occurrence of acute pancreatitis." (PMID 38333760, 2024). "The role of IL-6 in the early and accurate prediction of the severity of acute pancreatitis has been reported in multiple studies." (PMID 39337656, 2024). "It was reported that proinflammatory cytokines such as TNF-α and IL-6 levels significantly increased in acute pancreatitis." (PMID 38333760, 2024). "We defined this group as “severe illness” and included the following conditions: severely injured polytrauma patients, patients with ARDS requiring veno-venous-ECMO, severely ill patients with an IL-6 ≥ 10,000 pg/ml and patients with severe acute pancreatitis." (PMID 37259160, 2023). "Serum IL-1β, IL-6 and IL-10 concentrations have been shown to increase after 6 to 12 h of severe acute pancreatitis in pigs." (PMID 37175426, 2023). "Acute pancreatitis is also characterized by increases in pancreatic pro-inflammatory cytokines and chemokines, including IL-1β, IL-6, IL-8, and monocyte chemoattractant protein-1 (MCP-1) which drive inflammation and tissue damage." (PMID 37180135, 2023). "Multi-factorial logistic regression analysis suggested that PASS, IL-6, PCT and WBC were independent risk factors for acute pancreatitis predicting severity of the disease." (PMID 37680829, 2023). "The inhibition of ADAM17 results in decreased IL-6 trans signaling and was shown to ameliorate the disease severity of acute pancreatitis." (PMID 37881430, 2023).
acute pancreatitis (continued). "It was shown that the level of Il-6 and Il-1β corresponds with the severity of acute pancreatitis and the overexpression of Il-1β in the murine induces chronic pancreatitis." (PMID 37371528, 2023). "A significant increase in IL-6 levels has been demonstrated in the course of acute pancreatitis, and it is possible that an early increase in IL-6 levels leads to chronic hyperglycemia after resolution of the acute disease." (PMID 36979645, 2023). "The serum IL-6 concentration is elevated significantly in severe and fatal cases with the acute pancreatitis, as well as in cases complicated with pulmonary and renal failure." (PMID 35205334, 2022). "In vivo, alpha-pinene pretreatment reduced the production of the pancreatic tumor necrosis factor, interleukin (IL)-1beta, and IL-6 during the induction of acute pancreatitis by cerulean." (PMID 35495945, 2022). "Plasma amylase, IL-6, and IL-1β levels were significantly elevated in acute pancreatitis groups (p < 0.05)." (PMID 36945982, 2022). "The effects of the infusion of ADSCs on the production of pro-inflammatory cytokines (IL-6 and TNF-α) linked to acute pancreatitis were examined." (PMID 35597800, 2022). "In the acute pancreatitis groups, serum amylase, IL-6, and IL-1b levels were statistically significantly raised compared to the sham group (P < .01)." (PMID 36262104, 2022). "It has been reported that the production of pro-inflammatory cytokines, including TNF-α, IL-1β and IL-6, is a vital player in the pathogenesis of acute pancreatitis." (PMID 35042436, 2022). "In the course of acute pancreatitis, interleukin-6 plays an important role as a mediator in the inflammatory response." (PMID 35205334, 2022). "Plasma amylase, IL-6, and IL-1β levels in the groups with acute pancreatitis were significantly increased when compared to the sham group (p < 0.01)." (PMID 36945982, 2022). "In acute pancreatitis, IL-2, IL-6, IL-8, IL-10, and nitric oxide also contribute to this systemic effect mechanism." (PMID 36262104, 2022). "Excessive intracellular ROS levels upregulate the expression of the inflammatory cytokine IL-6, which contributes to acute pancreatitis." (PMID 35326169, 2022). "So far, some cross-sectional studies have shown that serum levels of IL6 and TNF-a are elevated after acute pancreatitis and are associated with chronic hyperglycemia after pancreatitis (CHAP)." (PMID 35498402, 2022). "Cerulein, a cholecystokinin analog, induces calcium (Ca2+) overload, oxidative stress, and IL-6 expression in pancreatic acinar cells, which are hallmarks of acute pancreatitis." (PMID 34349610, 2021). "There have been no human studies evaluating tocilizumab, a monoclonal antibody that competitively inhibits the binding of IL-6 to its receptor, in the treatment of acute pancreatitis." (PMID 34945198, 2021). "They therefore concluded that IL-6 is a useful marker for assessment of the severity of acute pancreatitis in its early stages." (PMID 34349610, 2021). "Acute pancreatitis is a common clinical condition with increasing the proinflammatory mediators, including interleukin-6 (IL-6)." (PMID 34349610, 2021). "During acute pancreatitis, injured pancreatic acinar cells release a series of proinflammatory mediators such as IL-6, which promote the recruitment and activation of immune cells." (PMID 34349610, 2021). "We investigated the mechanism by which DHA suppresses ROS-mediated expression of pro-inflammatory cytokine IL-6 in cerulein-stimulated AR42J cells which has been used as an in vitro model of acute pancreatitis." (PMID 33158207, 2020). "Electroacupuncture also has therapeutic effect on acute pancreatitis by decreasing IL-6, leading to reducing the inflammatory response." (PMID 33144870, 2020).